VAV1 (vav guanine nucleotide exchange factor 1)
Description:
Couples tyrosine kinase signals with the activation of the Rho/Rac GTPases, thus leading to cell differentiation and/or proliferation.
Synonyms: VAV
Tractability: Small molecule: a structure with a bound ligand is known. Antibody: its Gene Ontology location is reachable by antibodies, with high confidence. PROTAC: ubiquitination databases record sites on it; its protein half-life has been measured; a small molecule that binds it is known.
Gene: Protein-coding gene on chromosome 19 (6,772,694 to 6,857,366, forward strand). Ensembl gene ENSG00000141968.
Subcellular location (Human Protein Atlas): Cytosol
Pathways (Reactome):
Signal Transduction: Erythropoietin activates RAS; G alpha (12/13) signalling events; NRAGE signals death through JNK; PI5P, PP2A and IER3 Regulate PI3K/AKT Signaling; PIP3 activates AKT signaling; RAC1 GTPase cycle; RAC2 GTPase cycle; RHOA GTPase cycle; RHOG GTPase cycle; Signaling by SCF-KIT; VEGFA-VEGFR2 Pathway; VEGFR2 mediated vascular permeability
Immune System: Antigen activates B Cell Receptor (BCR) leading to generation of second messengers; CD28 dependent Vav1 pathway; FCERI mediated Ca+2 mobilization; FCERI mediated MAPK activation; Interleukin-3, Interleukin-5 and GM-CSF signaling; Regulation of actin dynamics for phagocytic cup formation; Regulation of signaling by CBL
Disease: Constitutive Signaling by Aberrant PI3K in Cancer; FCGR3A-mediated phagocytosis; Potential therapeutics for SARS
Drug ADME: Azathioprine ADME
Hemostasis: GPVI-mediated activation cascade
Gene Ontology:
Molecular function: guanyl-nucleotide exchange factor activity; phosphotyrosine residue binding; protein binding; phosphorylation-dependent protein binding
Biological process: natural killer cell activation; natural killer cell mediated cytotoxicity; T cell costimulation; B cell proliferation; cell migration; cellular response to xenobiotic stimulus; Fc-epsilon receptor signaling pathway; Fc-gamma receptor signaling pathway involved in phagocytosis; immune response-regulating cell surface receptor signaling pathway; platelet activation; positive regulation of phosphatidylinositol 3-kinase/protein kinase B signal transduction; regulation of small GTPase mediated signal transduction; small GTPase-mediated signal transduction; vascular endothelial growth factor receptor signaling pathway; intracellular signal transduction; response to xenobiotic stimulus
Cellular component: cytoplasm; cytosol; plasma membrane; cell-cell junction
Genetic constraint (gnomAD): Loss-of-function variants: 33 observed, 125.16 expected, observed/expected ratio (o/e) 0.26, 90% interval 0.2 to 0.35. The upper end of that interval is the gene's LOEUF score, 0.35, which puts it in group 1 of 6, group 1 being the genes least tolerant of losing a copy. Missense variants: 715 observed, 1,085.2 expected, observed/expected ratio (o/e) 0.66, 90% interval 0.62 to 0.7. Synonymous variants: 394 observed, 411.49 expected, observed/expected ratio (o/e) 0.96, 90% interval 0.88 to 1.04.
Homologues: Orthologues: chimpanzee VAV1 (100% identical), macaque VAV1 (97% identical), dog VAV1 (96% identical), pig VAV1 (96% identical), mouse Vav1 (93% identical), rat Vav1 (93% identical), tropical clawed frog vav1 (70% identical), rabbit VAV1 (68% identical). Paralogues in human: VAV3 (59% identical), VAV2 (52% identical), MCF2L (16% identical), KALRN (16% identical), PLEKHG4B (16% identical), TRIO (15% identical), TIAM2 (15% identical), ARHGEF7 (15% identical), TIAM1 (15% identical), MCF2 (15% identical), PLEKHG1 (14% identical), PLEKHG4 (14% identical), and 10 more.
Diseases named in the same sentence as VAV1 in open-access papers:
VAV1 is named in the same sentence as 126 diseases in open-access papers, as found by Europe PMC text mining. Sharing a sentence is not in itself a finding about the gene and the disease. The quoted sentences say what the papers report.
pancreatic cancer (25 papers, 2012 to 2025). "Rac1 and two of its GEFs, Tiam1 and Vav1, have been reported to be overexpressed in more than 70% of pancreatic cancers, and Vav1 overexpression has also been associated with poor prognosis in pancreatic cancer patients." (PMID 25344910, 2014). "Aberrant expression of Vav1, a Vav family member of GEFs, is frequently observed in pancreatic cancer and associated with active Rac1 and worse prognosis." (PMID 23408967, 2013). "Overexpression of Vav1 has also been associated with poor prognosis of pancreatic cancer patients." (PMID 28410221, 2017). "Also, Vav1 was shown to promote the matrix-degrading processes underlying pancreatic tumor cell migration through its GEF activity." (PMID 25313137, 2014). "In pancreatic cancer cells, VAV1 triggers the guanine nucleotide exchange of Cdc42 and is a major driver of invadopodium assembly." (PMID 40126693, 2025). "Even if its prognostic role is controversial, the expression of Vav1 in pancreatic cancer was correlated to signal transduction processes responsible for aggressive malignant phenotypes." (PMID 33165749, 2021). "Overall, our data demonstrate that the in vitro achievement of insulin-producing cells as a result of ATRA-induced differentiation of precursors or pancreatic cancer cells is almost completely dependent from Vav1, whose expression is in turn regulated by ATRA." (PMID 33165749, 2021). "The mutant K-RasG12D is present in nearly 90% of human pancreatic cancers, and is, thus, sometimes co-expressed with endogenous Vav1." (PMID 32277014, 2020). "Taken together, our results thus point, for the first time, to the role played by Vav1 in the initial stages of pancreatic cancer development." (PMID 32277014, 2020). "In a recent study, azathioprine also blocked Vav1 signaling in pancreatic tumor cells, inhibiting cell migration, and decreasing metastasis in mouse models." (PMID 32322580, 2020). "Vav1 also regulated pancreatic cancer cell migration via Rac1, and its expression was correlated with pancreatic cancer cell lines but not in the normal human pancreas." (PMID 32322580, 2020). "Sequence analysis of Vav1 cDNA from pancreatic cancer cell lines and tumors confirmed their expression of intact wild-type (wt) Vav1." (PMID 32277014, 2020). "To study the contribution of Vav1 to the development of pancreatic cancer tumors, we first generated a Vav1 transgenic mouse line." (PMID 32277014, 2020). "Here, we report the involvement of Vav1 in pancreatic cancer development and growth by using a novel transgenic mouse model, in which Vav1 is specifically expressed in pancreatic acinar cells." (PMID 32277014, 2020). "Depletion of Vav1 in pancreatic cancer cells and in lung cancer demonstrated a reduction in Rac1 activity." (PMID 30297765, 2018). "The identity of wild-type Vav1 from pancreatic cancer cell lines and tumors was confirmed by sequence analysis." (PMID 30297765, 2018). "Patients that carried pancreatic tumors expressing Vav1 had a poorer prognosis than those whose tumors were Vav1-negative." (PMID 30297765, 2018). "Many GEFs such as Vav1 and Tiam1 that are overexpressed in pancreatic cancer are known to promote Rac1 activation." (PMID 28410221, 2017). "In PDAC progression the RAC1 GEF VAV1 has been shown to possess a role by acting synergistically with the EGFR to stimulate pancreatic tumor cell proliferation." (PMID 28499439, 2017). "For its proliferative effect VAV1 needs to be stabilized by dynamin 2, which also potentiates invasive migration of pancreatic tumor cells." (PMID 28499439, 2017). "For example, the guanine nucleotide exchange factor VAV1, which is an activator of Rho family GTPases, is unregulated in many pancreatic cancers, where it facilitates the survival and migration of tumor cells." (PMID 28029655, 2017).
pancreatic cancer (continued). "More recently, in pancreatic tumor cells, dynamin 2 was found to promote lamellipodia formation and pancreatic tumor cell migration by its direct binding with Vav1 to promote Rac1 activation and migration." (PMID 28402939, 2017). "For example, TGF-β promotes epithelial to mesenchymal transition (EMT) of pancreatic cancer cells partially by inducing hypermethylation of CpG site in VAV1 gene body and VAV1 expression." (PMID 27999365, 2016). "VAV guanine nucleotide exchange factor 1 (VAV1) is reported to be overexpressed in clinical pancreatic carcinoma cells, leading to activation of Rac1 signaling, resulting in decreased survival in pancreatic cancer patients." (PMID 27145964, 2016). "For instance, specific depletion of only Vav1 in pancreatic cancer cell lines led to inhibition of their growth, despite the continuous expression of Vav2." (PMID 26353933, 2015). "Sequence analysis of the Vav1 cDNA from pancreatic cancer cell lines and tumors confirmed that they express intact wild-type Vav1." (PMID 26353933, 2015). "This process requires Vav1 activation of Cdc42, demonstrating that in pancreatic tumor cells, ectopically expressed Vav1 can signal through multiple pathways." (PMID 26353933, 2015). "Elevated expression of Vav1 has been demonstrated to affect cell proliferation in lung cancer and pancreatic cancer cells." (PMID 24905577, 2014). "Recent studies in pancreatic cancer and lung cancer cells that express Vav1 clearly showed that Vav1 functions as a GEF for Rac1 GTPase following EGF stimulation." (PMID 25313137, 2014). "Recent studies in pancreatic cancer and lung cancer cells that express Vav1 showed that Vav1 functions as a GEF for Rac1 GTPase following EGF stimulation and that this activity is critical for its function." (PMID 23342133, 2013). "It has been demonstrated that epigenetic modifications, including methylation, play an important role in aberrant vav1 expression in pancreatic cancer cell lines." (PMID 22253833, 2012). "To date, however, the mechanisms that mediate this protumorigenic role of Vav1 in pancreatic cancer and the stages during tumorigenesis, at which such mediation occurs, are unknown." (PMID 32277014, 2020). "Furthermore, metastasis in a pancreatic cancer mouse model was shown to be inhibited with azathioprine through inhibition of the activity of Vav1 as a GEF towards Rac1." (PMID 32277014, 2020). "The well-known function of Vav1 as the tyrosine phosphorylation–dependent GEF activity for Rac1 was previously shown to be linked to an increase in tumorigenic properties of pancreatic cancer." (PMID 32277014, 2020). "The synergy observed here between Vav1 and K-RasG12D in the development of pancreatic cancer could conceivably stem from signaling pathways in which both Vav1 and K-RasG12D participate." (PMID 32277014, 2020). "The aberrant expression of Vav1 in pancreatic cancer was attributed to epigenetic changes." (PMID 32277014, 2020). "Furthermore, Vav1 RNAi was found to abolish neoplastic cellular proliferation of human pancreatic cancer cell lines both in vitro and in vivo, even in the presence of oncogenic K-Ras." (PMID 32277014, 2020). "Moreover, demethylation of VAV1 in the promoter region was shown to increase Vav1 expression in pancreatic cancer, and targeting Vav1 inhibited pancreatic cancer metastasis." (PMID 32322580, 2020). "In pancreatic cancers, more than 70% of tumors overexpressed the Rac1 GEFs Tiam1 and Vav1." (PMID 28410221, 2017). "Thus, reduction of Vav2 and Vav3 expression in mouse mammary tumor cells led to a decline in metastatic growth, similar to the effect of Vav1 depletion in pancreatic cancer cells." (PMID 26353933, 2015). "Furthermore, it was demonstrated that the large GTPase Dynamin 2 potentiates invasive migration of pancreatic tumor cells through stabilization of the Rac1 GEF Vav1." (PMID 25313137, 2014).
pancreatic cancer (continued). "In addition, patients with Vav1-positive pancreatic tumors exhibit poorer prognosis and lower survival rate than those with Vav1-negative tumors, suggesting that the ectopic expression of Vav1 plays an innegligible role in tumor development and progression." (PMID 24905577, 2014). "Thus, when expressed ectopically, Vav1 is considered to function as a central regulator and major driver of invasive matrix remodeling by pancreatic tumor cells." (PMID 25313137, 2014). "As Vav1 is also involved in cell proliferation in lung cancer and pancreatic cancer cells, we speculated that Vav1 participated in cell cycle progression of breast cancer cells under the control of E2." (PMID 24905577, 2014). "Rac1 and two of its GEFs, Tiam1 and Vav1, are overexpressed in more than 70% of pancreatic cancers." (PMID 25344910, 2014). "Recent studies in pancreatic cancer and lung cancer cells showed that ectopically expressed Vav1 acts as an upstream activator of Rac1, RhoA and possibly Cdc42 signaling pathways in response to extracellular stimulation, leading to cytoskeleton changes in cancer cells." (PMID 23342133, 2013). "This study also showed that treatment of pancreatic cells that do not express Vav1 with DNA demethylation agents lead to Vav1 expression, suggesting that ectopic expression of Vav1 in primary pancreatic cancer is the result of an epigenetic modification of the vav1 gene regulatory sequences." (PMID 22253833, 2012). "Moreover, our data reveal the need for a reassessment of the role of Vav1 in pancreatic cancer and suggest that nuclear accumulation of this protein may be a PDAC prognostic factor." (PMID 32993067, 2020). "Indeed, as shown in pancreatic cancer cells, EGF stimulation leads to tyrosine phosphorylation of Vav1, followed by the activation of a Rac1/Pak1/NF-κB signaling pathway resulting in an increase in cyclin D1 which leads to enhanced pancreatic tumor cell proliferation." (PMID 26353933, 2015). "Here, using models of pancreatic ductal adenocarcinomas (PDAC), the most common subtype of pancreatic cancer, we provide evidence of a novel mechanism driving oncogenic gene expression in PDAC cells that is regulated by nuclear VAV1." (PMID 41314543, 2025). "Azathioprine, an agent that blocks VAV1 GEF activity, was shown to prevent metastasis in a mouse model of pancreatic cancer by inhibiting VAV1 function." (PMID 37174676, 2023). "It has been shown that VAV1 requires both its GEF function leading to RAC1 activation and downstream signaling pathways to contribute to the oncogenicity of pancreatic cancer cells." (PMID 37174676, 2023). "Also considering that the over-expression of Vav1 is sufficient to up-modulate the epithelial marker CK7, our data suggest that the role of Vav1 in pancreatic tumor cells could be reconsidered on the basis of its ability to act as a direct promoter of an epithelial-like phenotype." (PMID 33165749, 2021). "In particular, the increase of Vav1 was maximum with 1 μM ATRA, known to induce re-differentiation or trans-differentiation of pancreatic cancer cells." (PMID 33165749, 2021). "VAV1 inhibits the metastasis and therapy resistance by downregulating the Akt2 (AKT serine/threonine kinase 2) signaling pathway in pancreatic cancer." (PMID 34335756, 2021). "We found that the accumulation of Vav1 inside the nucleus inversely correlates with Akt2 expression in both PDAC-derived cells and pancreatic tumor tissues." (PMID 32993067, 2020). "Our experiments excluded the involvement of miR-615, targeting Akt2 in MDA-MB-231 and pancreatic cancer cells, as it was not modified by Vav1 levels in this cell model." (PMID 35743776, 2022). "Le2 was also transfected into vav1-negative cell lines: lung cancer cells H460 and A549) and pancreatic cancer cell line Panc1." (PMID 22253833, 2012). "Panc1 cells do express Vav1 following transfection, indicating that the vav1 gene is not appropriately methylated in Vav1-expressing cell lines and pancreatic tumor specimens." (PMID 22253833, 2012).
pancreatic cancer (continued). "PDAC patients with Vav1-positive tumors have a worse prognosis compared to patients with Vav1-negative tumors, and the ability of Vav1 to promote the growth of pancreatic cancer cells was correlated to its best-known function as a guanosine exchange factor (GEF)." (PMID 32993067, 2020). "Moreover, knockdown of Vav2 in these cells did not alter their growth, suggesting that Vav1 and Vav2 play different roles in pancreatic cancer cells." (PMID 26353933, 2015).